BRD7 (bromodomain containing 7)
Description:
Acts both as coactivator and as corepressor. May play a role in chromatin remodeling. Activator of the Wnt signaling pathway in a DVL1-dependent manner by negatively regulating the GSK3B phosphotransferase activity. Induces dephosphorylation of GSK3B at 'Tyr-216'. Down-regulates TRIM24-mediated activation of transcriptional activation by AR (By similarity). Transcriptional corepressor that down-regulates the expression of target genes. Binds to target promoters, leading to increased histone H3 acetylation at 'Lys-9' (H3K9ac). Binds to the ESR1 promoter. Recruits BRCA1 and POU2F1 to the ESR1 promoter. Inhibits cell cycle progression from G1 to S phase.
Synonyms: BP75; CELTIX1; SMARCI1; NAG4
Tractability: Small molecule: a structure with a bound ligand is known; a high-quality ligand is known. PROTAC: it is named in the literature on targeted protein degradation; UniProt records ubiquitination sites on it; ubiquitination databases record sites on it; its protein half-life has been measured; a small molecule that binds it is known.
Target class: Epigenetic regulator; Bromodomain; Reader
Chemical probes: BI-7273 (high quality), BI-9564 (high quality), LP99 (high quality), TP-472 (high quality), VZ185 (high quality)
Gene: Protein-coding gene on chromosome 16 (50,313,487 to 50,368,988, reverse strand). Ensembl gene ENSG00000166164.
Subcellular location: Nucleus; Chromosome; Nucleus (Isoform 2)
Subcellular location (Human Protein Atlas): Nucleoplasm; Cytosol
Pathways (Reactome):
Chromatin organization: Formation of the polybromo-BAF (pBAF) complex
Gene Ontology:
Molecular function: histone binding; histone H3K14ac reader activity; protein binding; transcription cis-regulatory region binding; transcription coactivator activity; transcription corepressor activity; histone reader activity
Biological process: negative regulation of DNA-templated transcription; negative regulation of G1/S transition of mitotic cell cycle; regulation of mitotic cell cycle; regulation of transcription by RNA polymerase II; transcription initiation-coupled chromatin remodeling; chromatin remodeling; positive regulation of cell differentiation; positive regulation of double-strand break repair; positive regulation of myoblast differentiation; positive regulation of T cell differentiation; regulation of G0 to G1 transition; regulation of G1/S transition of mitotic cell cycle; regulation of mitotic metaphase/anaphase transition; regulation of nucleotide-excision repair; positive regulation of DNA-templated transcription
Cellular component: chromosome; nucleoplasm; nucleus; chromatin; cytoplasm; kinetochore; nuclear matrix; RSC-type complex
Genetic constraint (gnomAD): Loss-of-function variants: 14 observed, 65.12 expected, observed/expected ratio (o/e) 0.22, 90% interval 0.14 to 0.34. The upper end of that interval is the gene's LOEUF score, 0.34, which puts it in group 1 of 6, group 1 being the genes least tolerant of losing a copy. Missense variants: 570 observed, 658.79 expected, observed/expected ratio (o/e) 0.87, 90% interval 0.81 to 0.93. Synonymous variants: 208 observed, 236.81 expected, observed/expected ratio (o/e) 0.88, 90% interval 0.78 to 0.99.
Homologues: Orthologues: chimpanzee BRD7 (99% identical), macaque BRD7 (99% identical), pig BRD7 (94% identical), dog BRD7 (93% identical), rabbit BRD7 (91% identical), guinea pig BRD7 (91% identical), mouse Brd7 (88% identical), rat Brd7 (88% identical), tropical clawed frog brd7 (60% identical), zebrafish brd7 (52% identical), Drosophila melanogaster Brd7-9 (32% identical), Caenorhabditis elegans swsn-9 (25% identical). Paralogues in human: BRD9 (33% identical), YBEY (6% identical).
Diseases named in the same sentence as BRD7 in open-access papers:
BRD7 is named in the same sentence as 68 diseases in open-access papers, as found by Europe PMC text mining. Sharing a sentence is not in itself a finding about the gene and the disease. The quoted sentences say what the papers report.
nasopharyngeal carcinoma (22 papers, 2008 to 2026). A carcinoma arising from the nasopharyngeal epithelium. "Association between the expression of BRD7, BRD7 methylation index and nasopharyngeal carcinoma (NPC) clinical pathological features (n = 45)." (PMID 41510594, 2026). "One of the 4 feature genes, BRD7 is an oncogene widely expressed in various human tissues and has been extensively studied as a nasopharyngeal carcinoma-associated gene." (PMID 37378023, 2023). "Hypermethylation of BRD7 promoter CpG island is a critical mechanism leading to the downregulation of BRD7 expression in nasopharyngeal carcinoma (NPC)." (PMID 41510594, 2026). "Recently, circBRD7 was shown to promote the transcriptional activation and expression of its host gene BRD7 by increasing the acetylation of histone 3, thus suppressing the growth and metastasis of nasopharyngeal carcinoma." (PMID 40612865, 2025). "BRD7 is a candidate tumor suppressor gene and nuclear transcription factor of nasopharyngeal carcinoma (NPC) which was cloned in our laboratory." (PMID 40083706, 2025). "Accumulating evidences have demonstrated that BRD7 is downregulated in many types of cancers, including nasopharyngeal carcinoma, ovarian cancer, gastric cancer, breast cancer and prostate cancer." (PMID 36788209, 2023). "Reduced expression of BRD7 has been reported in various types of tumors, including nasopharyngeal carcinoma, breast cancer, and colorectal carcinoma, indicating that BRD7 functions as a tumor suppressor." (PMID 37626049, 2023). "BRD7 functions as a crucial tumor suppressor in numerous malignancies including nasopharyngeal carcinoma (NPC)." (PMID 36788209, 2023). "Bromodomain-containing protein 7 (BRD7) was found to be down-expressed in nasopharyngeal carcinoma as well as breast cancer and to function as a potential tumor suppressor." (PMID 35371302, 2022). "To date, considerable evidence has shown that BRD7 is commonly downregulated in many malignancies, such as nasopharyngeal carcinoma, epithelial ovarian cancer, and breast cancer, and BRD7 functions as a tumor suppressor." (PMID 34109174, 2021). "Bromodomain-containing protein 7 (BRD7), first cloned from nasopharyngeal carcinoma cells, is involved in multiple physiological processes via mediation of chromatin remodeling 7-9." (PMID 33531996, 2021). "In our previous studies, we found that BRD7 inhibits cell proliferation and tumor growth by maintaining cell cycle G1/S phase arrest in nasopharyngeal carcinoma cells." (PMID 34109174, 2021). "BRD7 was first discovered as a gene that is downregulated in nasopharyngeal carcinoma (NPC) biopsies." (PMID 32992509, 2020). "Previous studies showed that BRD7 gene exhibited much higher-level of mRNA expression in normal nasopharyngeal epithelia than in nasopharyngeal carcinoma (NPC) biopsies and cell lines." (PMID 19111069, 2008). "BRD7 was first identified as downregulated in nasopharyngeal carcinoma." (PMID 39580422, 2024). "For example, BRD7 was down-regulated in nasopharyngeal carcinoma, prostate cancer and epithelial ovarian carcinoma and could inhibit cell growth through multiple mechanisms, including cell cycle arrest." (PMID 24840027, 2014). "For example, down-regulation of BRD7 was reported in nasopharyngeal carcinoma and prostate cancer, and its inhibition of cell growth probably occurs through transcriptional regulation of ras/MEK/ERK, Rb/E2F, beta-catenin, which in turn affects progression of the cell cycle." (PMID 24840027, 2014). "BRD7 has been confirmed to be lowly expressed in nasopharyngeal carcinoma (NPC) tissues and exerts tumour suppressive roles." (PMID 41510594, 2026). "BRD7 was originally identified as a tumor suppressor that inhibits nasopharyngeal carcinoma (NPC) cell growth by negatively regulating the beta-catenin and ERK pathways." (PMID 26919247, 2016). "BRD7 is a bromodomain-containing gene identified from Nasopharyngeal carcinoma (NPC) cells by cDNA Representational Difference Analysis." (PMID 19111069, 2008).
nasopharyngeal carcinoma (continued). "For instance, BRD7 negatively regulated the transcriptional activity and expression of baculoviral IAP repeat containing 2 (BIRC2), which functions as an oncogene in nasopharyngeal carcinoma." (PMID 39580422, 2024). "Bromodomain-containing protein 7 (BRD7) is a member of the bromodomain-containing protein family, and was discovered two decades ago as a protein that is downregulated in nasopharyngeal carcinoma." (PMID 32992509, 2020). "BRD7 functions as a tumor suppressor in multiple cancers, including nasopharyngeal carcinoma (NPC)." (PMID 27010857, 2016). "In addition, BRD7 arrests cell cycle progression from G1 to S phase by regulating cell cycle-related molecules, such as cyclin D1 and E2F3, in nasopharyngeal carcinoma." (PMID 37626049, 2023). "In our laboratory, BRD7 has been reported as absent or expressed at unusually low levels in nasopharyngeal carcinoma (NPC) biopsies, and overexpression of BRD7 inhibits NPC cell growth and arrest cells in the G0/G1 phase of the cell cycle." (PMID 24404152, 2014).
breast carcinoma (18 papers, 2012 to 2026). "Loss of BRD7 or BRCA1 in breast cancer cells prevents expression of ERα, and makes the cells resistant to fulvestrant, an antiestrogen drug that is often used to treat breast cancer." (PMID 32992509, 2020). "Our previous study reported that BRD7 promotes PTX-mediated breast cancer cell apoptosis and enhances the chemosensitivity of PTX by upregulating Bak expression at the transcription level." (PMID 41315221, 2025). "In a word, the TRIM25/BRD7 signaling axis is indeed related to the paclitaxel resistance in breast cancer." (PMID 41315221, 2025). "Our previous studies demonstrated that BRD7 participates in the paclitaxel-mediated chemotherapy sensitization and inhibits the malignant progression of breast cancer." (PMID 41315221, 2025). "Herein, we further clarify the clinical value and significance of the expression of TRIM25 and BRD7 in patients with breast cancer." (PMID 41315221, 2025). "BRD7 has been reported to be involved in breast cancer proliferation, invasion, metastasis, and PTX resistance." (PMID 41315221, 2025). "Our previous study showed that BRD7 was an unstable protein in breast cancer, and that the ubiquitin-proteasome pathway was involved in the regulation of BRD7 protein instability." (PMID 41315221, 2025). "Our previous study showed that BRD7 was an unstable protein in breast cancer, and the ubiquitin-proteasome pathway was involved in the regulation of BRD7 protein instability." (PMID 41315221, 2025). "The dysregulation of BRD7 expression in breast cancer is an important mechanism leading to tumor occurrence, development, and PTX resistance." (PMID 41315221, 2025). "Taken together, these results indicate that TRIM25 directly interacts with BRD7 in breast cancer cells." (PMID 41315221, 2025). "YB1 has also been identified as an interacting protein of BRD7 in breast cancer; BRD7 binds to the C-terminus of YB1 through its N-terminus, thus promoting YB1 ubiquitination and degradation." (PMID 39664566, 2024). "BRD7 is a tumor suppressor known to inhibit cell proliferation and cell cycle progression and to induce apoptosis in breast cancer." (PMID 34948142, 2021). "Both Niu and our study confirmed the oncogenic role of bromodomain-containing 7 (BRD7) molecule in breast cancer." (PMID 34507558, 2021). "A series of twelve cancer driver gene expressions were identified to be associated with transcription factors, of which CCR7, BRD7, DDX3X, and UBE2A were upregulated in breast cancer tissues, and the others were downregulated in breast cancer tissues." (PMID 34507558, 2021). "A variety of targets, such as estrogen receptor α (ERα), are regulated by BRD7 and BRCA1 coordinately in breast cancer, and BRD7 regulates ERα transcription by recruiting BRCA1 and Oct-1 to the promoter of ESR1 (the gene encoding ERα)." (PMID 34671561, 2021). "The results in vivo and in vitro indicate that BRD7 inhibits tumor growth and lung metastasis in breast cancer through the regulation of YB1." (PMID 32028981, 2020). "CCK8 assay showed that BRD7 overexpression significantly inhibited the growth of breast cancer cells compared with control cells but restoration of YB1 expression recovers the inhibitory effect of BRD7 on cell proliferation in MDA231 and MCF7 cells." (PMID 32028981, 2020).
breast carcinoma (continued). "To further explore the specific molecular mechanism by which BRD7 is involved in breast cancer invasion and metastasis, we screened the proteins interacting with BRD7." (PMID 32028981, 2020). "Immunohistochemistry (IHC) of breast cancer and normal tissues confirmed that the low expression and mainly nuclear localization of BRD7 is present in tumor tissues and a high level of BRD7 is viewed as a positive prognostic factor." (PMID 32028981, 2020). "Since then, decreased expression of BRD7 has been reported in many other human cancers including breast cancer, ovarian cancer, osteosarcoma, pancreatic cancer, colorectal cancer, and lung adenocarcinoma." (PMID 32992509, 2020). "BRD7 is a tumor suppressor known to inhibit cell proliferation and cell cycle progression and initiate apoptosis in breast cancer." (PMID 32028981, 2020). "Collectively, these findings uncover that BRD7 blocks tumor growth, migration and metastasis by negatively regulating YB1-induced EMT, providing new insights into the mechanism by which BRD7 contributes to the progression and metastasis of breast cancer." (PMID 32028981, 2020). "Moreover, we further validated that high TRIM25 expression predicts poor prognosis of BC patients, and a combination of TRIM25 and BRD7 expression is an effective marker for the prognosis of breast cancer." (PMID 41315221, 2025). "Accordingly, targeting the TRIM25/BRD7/YB1/Bcl-2 signal axis may be a potential molecular target for early diagnosis of breast cancer and promoting the sensitization of PTX in clinical breast cancer patients." (PMID 41315221, 2025). "In our previous study, Y-box binding protein-1 (YB1), a transcriptional activator, was identified as a novel interacting protein of BRD7 in breast cancer, and BRD7 suppressed cell proliferation and EMT-mediated invasion and metastasis in breast cancer by negatively regulating YB1." (PMID 41315221, 2025). "The suppressive role of BRD7 in cancers has been well recognized, whereas the mechanism of BRD7 in PTX resistance in breast cancer remains unclear." (PMID 41315221, 2025). "Overall, these data identified that the TRIM25/BRD7 axis could guide the early diagnosis and treatment in breast cancer patients and provide a potential therapeutic target for breast cancer therapy." (PMID 41315221, 2025). "Our findings demonstrate that targeting the TRIM25/BRD7/YB1/Bcl-2 signal axis might be a potential therapeutic strategy for the treatment of breast cancer." (PMID 41315221, 2025). "Additionally, BRD7 was downregulated in various cancers, such as breast cancer, cervical cancer, ovarian cancer, and gastric cancer 32-35." (PMID 40083706, 2025). "The expression of TRIM25 was negatively correlated with BRD7 expression, and the combined expression of TRIM25 and BRD7 might be a potential molecular marker for the prediction of malignant progression and prognosis of breast cancer." (PMID 41315221, 2025). "Indeed, BRD7 is recognized as a tumor suppressor in several types of cancer; in breast cancer, the survival of patients exhibiting nuclear BRD7 is significantly prolonged vs patients showing cytoplasmic BRD7." (PMID 39695102, 2024).